VRK1 (VRK serine/threonine kinase 1)
Diseases named in the same sentence as VRK1 in open-access papers (continued):
Sharing a sentence is not in itself a finding about the gene and the disease.
tumor (continued). "Based on the in vitro studies, circ-VRK1 expression is down modulated in BC cell lines comprising MDA-MB-231, BT474 and MDA-MB-453 relative to the normal immortalized breast epithelial cell lines (MCF10A), and circ-VRK1 represses tumor cell multiplication." (PMID 33718157, 2021). "We have characterized the function of VRK1 in NB tumor cells and determined that VRK1 is an essential mediator of NB cell proliferation." (PMID 33233777, 2020). "To elucidate the possible implication of VRK1 in NB tumors, we explored the expression of VRK1 in several cohorts of human NB patient tumor samples, using expression data from public databases." (PMID 33233777, 2020). "MYCN-amplified tumor cells seem to be dependent on VRK1 expression for its exacerbated proliferation, raising the possibility of using VRK1 inhibitors for NB treatment as an alternative to MYCN targeting." (PMID 33233777, 2020). "Surprisingly, a transient and partial reduction of VRK1 expression in NB cells was enough to significantly impaired tumor growth in a xenograft mouse model." (PMID 33233777, 2020). "Tumor onset was delayed on mice injected with VRK1-depleted cells, and resulting tumors in these mice were significantly smaller." (PMID 33233777, 2020). "It is possible that VRK1 downregulation elicits a long-lasting epigenetic effect on NB tumor cells or that a high VRK1 expression is needed for the successful establishment of the tumor in the initial steps." (PMID 33233777, 2020). "The semi-quantitative IHC analysis score for staining intensity and the percentage of positively stained cells showed that high VRK1 expression (staining index (SI) ≥ 8) was observed in 59.84% (79/132) of tumor tissues." (PMID 29029460, 2017). "High VRK1 levels were detected in normal tissues with high proliferation such as the thymus and testis as well as in tumor tissues." (PMID 29029460, 2017). "In our work, VRK1 was overexpressed in ESCC tissues compared with that in adjacent non-tumor tissues." (PMID 29029460, 2017). "The role of VRK1 within the tumor phenotype is complex, since it can function as an oncogene or tumor suppressor depending on the cellular context." (PMID 27334688, 2016). "VRK1 knockdown inhibited the proliferation of SK-Hep1, SH-J1 and Hep3B cells; moreover, depletion of VRK1 suppressed HCC tumor growth in vivo." (PMID 26375549, 2015). "VRK1 levels were markedly higher in tumors than in non-tumor specimens (0.0000 versus 0.3182; mean 2−ΔCT values, P < 0.0001)." (PMID 26375549, 2015). "After 3, 4, 5 and 6 weeks of viral transduction, stable cell lines were subjected to Western blot analysis and colony formation assays to confirm the anti-tumor effect by sustained VRK1 knockdown." (PMID 26375549, 2015). "To investigate the contribution of VRK1 to tumor growth in vivo, we established SK-Hep1 cells expressing shRNA targeting VRK1 through transduction using a lentiviral vector." (PMID 26375549, 2015). "Significant downregulation of VRK1 was observed in the tumor tissues derived from VRK1 knockdown cells, as expected." (PMID 26375549, 2015). "In one way, VRK1 can interfere with cell cycle progression and division and thus prevent, or reduce, tumor growth and expansion." (PMID 24731990, 2014). "Another role by which VRK1 contributes to a poorer tumor prognosis can be due to its role in proliferation." (PMID 24731990, 2014).
tumor (continued). "VRK1 expression is specifically abundant in highly proliferative cells such as fetal and tumor tissues, and mainly displays a tendency to upregulate during the mitotic phase in the cell cycle." (PMID 25310002, 2014). "Once the inhibitory effect of luteolin mediated by binding to the catalytic domain of VRK1 was confirmed, we evaluated its anti-tumor effects on tumor cell proliferation and survival." (PMID 25310002, 2014). "In conclusion, our study suggests that luteolin is a small molecule inhibitor of the mitotic kinase VRK1, and induces cell cycle arrest and preferential cell death in tumor cells." (PMID 25310002, 2014). "VRK1 is highly expressed in both actively proliferating tissues, human tumor cell lines, and several tumor tissues suggesting that it plays an important role in cell cycle progression." (PMID 21179456, 2010). "Furthermore, VRK1 expression was upregulated in HCC patients corresponding to high tumor grade and cancer stage, indicating that VRK1 expression is positively correlated with the malignancy of liver tumor." (PMID 40234378, 2025). "Furthermore, hnRNPA1 directly binds to 3’-untranslated VRK1 mRNA, which contributes to its translation and tumor cell proliferation." (PMID 38753965, 2024). "High expression of VRK1 appears in different tumors and promotes tumor progression." (PMID 38157278, 2023). "Therefore, this study aims to evaluate the role of VRK1 on various cancers and to analyze the relationship between VRK1 and the prognosis of tumor patients." (PMID 38157278, 2023). "This suggests that VRK1 may play a role in modulating the tumor microenvironment and influencing the immune response in these specific cancers." (PMID 38157278, 2023). "Furthermore, we also looked at the relationship between the expression of VRK1 and the carcinogenesis process, specifically regarding MMR deficiencies and DNA methylation of vital tumor-related genes." (PMID 38157278, 2023). "Studies have reported that EMT plays an essential role in the molecular mechanism and treatment of tumor progression and metastasis, which implies that VRK1 may play a critical role in cancer oncogenesis and development by participating in EMT." (PMID 38157278, 2023). "In order to further detect the expression of VRK1 and proliferation-related proteins in tumor-bearing tissues, after fixing the tumor-bearing tissues, immunohistochemistry was used to detect the expression of VRK1 and Ki-67 proteins in the tumor-bearing tissues." (PMID 35559251, 2022). "Recently, some VRK1 specific inhibitors, based on an aminopyridine scaffold, are functional at pharmacological concentrations that inhibit tumor cell growth and effect similar to VRK1 depletion, however, still need testing to determine their therapeutic potential." (PMID 36011043, 2022). "Surprisingly, depletion of VRK1 with siRNA is transitory and tumors were collected after 8 weeks, indicating that VRK1 downregulation is somehow maintained in tumors and might have a profound and long-lasting influence on tumor establishment and growth." (PMID 33233777, 2020). "In this work we have studied the effect that VRK1 depletion has on the cellular response to olaparib, a drug which is currently used to sensitize tumor cell to ionizing radiation, and facilitates tumor elimination in cells with altered DNA repair pathways, such as those with BRCA1 or ATM mutations." (PMID 31101118, 2019). "Two opposing hypotheses would be that either overexpression of VRK1 might retard the shedding of metastatic cells from the primary tumor or conversely, it might enhance the colonization of distal sites by metastatic cells." (PMID 30180179, 2018). "The functions of VRK1 suggest that it is likely to actively participate in tumor biology." (PMID 29679095, 2018).
tumor (continued). "Taken together, these observations indicated that VRK1 counteracted the anti-tumor effects of CDDP." (PMID 29029460, 2017). "In this study, we show that VRK1 is overexpressed in ESCC primary tumor samples and cell lines." (PMID 29029460, 2017). "Taken together, our findings suggest VRK1 may act as a tumor promoter by controlling the level of cell cycle regulators associated with G1/S transition and could potentially serve as a therapeutic target and/or prognostic biomarker for HCC." (PMID 26375549, 2015). "Taken together, these findings suggest that VRK1 expression affects the proliferation of tumor cells, that VRK1 knockdown suppresses HCC cell growth in vitro and in vivo, and that the extent of its effect differs depending upon the basal VRK1 level in HCC cells." (PMID 26375549, 2015). "In addition, several studies have demonstrated that VRK1 depletion is able to impair tumor proliferation and metastasis." (PMID 25310002, 2014). "However, the molecular mechanism of VRK1 inhibition-induced anti-proliferative effects on tumor cells remains to be further described in detail to develop a novel chemotherapy strategy." (PMID 25310002, 2014). "There are several lines of evidence supporting an important role of VRK1 in tumor biology." (PMID 25310002, 2014). "Moreover, we found that VRK1 expression was upregulated in the tumor grade 3 and cancer stage T3." (PMID 40234378, 2025). "Furthermore, we found that VRK1 mutations do not occur in every tumor, such as LAML, THCA, UCS, and UVM." (PMID 38157278, 2023). "VRK1 might act as an important cell cycle regulator contributing to a poorer tumor prognosis." (PMID 34067799, 2021). "VRK1 expression also identifies patients with worse survival when classified into age at diagnosis groups, including groups in which it would be important to find new prognostic markers to identify patients with tumor progression, such as the ones diagnosed before 12 months of age." (PMID 33233777, 2020). "Moreover, a sustained reduction in VRK1 expression in tumor cells in vivo could be observed long after transfection." (PMID 33233777, 2020). "Furthermore, targeting VRK1 can also have additional effects on tumor progression." (PMID 31101118, 2019). "VRK1 plays a crucial role in cell proliferation and DNA repair processes, which, if inhibited, can lead to a reduction in tumor growth and an increase in its genetic instability that can be manipulated for therapeutic purposes, and perhaps also make the tumor more immunogenic." (PMID 31101118, 2019). "Therefore, UA, which specifically blocks VRK1, may also help to further understand tumor formation and reproductive sterility." (PMID 26412148, 2015). "Xenograft assays confirmed that depletion of VRK1 could suppress tumor growth in vivo." (PMID 26375549, 2015). "Another early study suggesting that VRK1 is an upstream kinase for 53BP1 foci formation in response to DNA damage implies that specific VRK1 inhibitors might contribute to additional DNA damage accumulation in tumor cells, thereby leading to tumor-specific cell death." (PMID 25310002, 2014). "Alternatively, VRK1 inhibition could emerge as a novel therapeutic target because it may facilitate the accumulation of toxic ROS in tumor cells in combination with other cancer drugs through the impairment of chromatin remodeling, resulting in decreased tumor cell viability and death." (PMID 38732093, 2024).
tumor (continued). "Moreover, in the context of HCC, VRK1 may act as an oncogene, actively promoting tumor progression." (PMID 38157278, 2023). "Concerning the expression pattern, VRK1 was detected in the nucleus, while VRK2 was observed mainly in the cytoplasm of tumor cells." (PMID 27456229, 2016). "This manuscript highlights novel data on the role of VRK1 and VRK2 in predicting tumor response to neoadjuvant chemoradiotherapy." (PMID 27456229, 2016). "VRK1 levels were significantly higher in HCC cell lines than a normal hepatic cell line, and were higher in HCC than non-tumor tissue." (PMID 26375549, 2015). "VRK1 depletion also impairs the accumulation of H4K20m2, similar to KMT inhibitors, which is necessary for the recruitment of 53BP1 in the non-homologous end joining (NHEJ) DNA damage repair pathway, thus sensitizing tumor cells to genotoxic treatments." (PMID 38753965, 2024). "Observed via mRNA and immunohistochemistry, in NB and patient-derived tumor xenograft (PDX)-derived cells, there is a strong positive correlation between the expression of VRK1 and that of the proliferation marker Ki67, as well as the mitotic index in the tumor." (PMID 36770809, 2023). "The involvement of three enzymes, VRK1, Tip60/KAT5 and SIRT2, in the regulation of the level of acetylation of H4K16 opens up the possibility of its pharmacological manipulation by their combination, to promote the elimination of tumor cells." (PMID 36902348, 2023). "We cannot rule out an influence of the tumor microenvironment on VRK1 expression and the proliferative potential of NB cells, not triggered in the case of tumor establishment with VRK1 knockdown cells." (PMID 33233777, 2020). "Despite being a target of MYCN transcription factor, VRK1 is a marker of tumor progression and malignancy independent of MYCN expression." (PMID 33233777, 2020). "We confirmed some of these genes, including VRK1, CSNK1A1 and PIK3R4, were also essential in a range of other human CRC lines, suggesting that they may represent cell or tumor-type specific vulnerabilities." (PMID 31891587, 2019). "The dual effect of VRK1 depletion on reduction of cell cycle progression and defective DDR implicates that the absence of this kinase in arrested tumor stem cells can facilitate the accumulation of mutations." (PMID 31101118, 2019). "Reports that VRK1 phosphorylates 53BP1, NBS1 and histone H2AX suggest that it may increase tumor resistance to DNA damage-based therapies." (PMID 30180179, 2018). "Compared with the adjacent non-cancerous tissues (ANCTs), the tumor tissues presented significant VRK1 overexpression." (PMID 29029460, 2017). "Notably, luteolin, a VRK1 inhibitor, suppresses HCC tumor growth by inhibiting cell proliferation and inducing cell death." (PMID 26375549, 2015). "A higher number of VRK1-positive cells was found in the tumor region than the adjacent non-tumor region." (PMID 26375549, 2015). "In addition, we detected the protein expression levels of VRK1 and SNAI1 from mice tumor tissues." (PMID 40234378, 2025). "Once we obtained specific aptamers against VRK1, other objective of this work was to study whether or not these aptamers could inhibit tumor progression in cells." (PMID 34067799, 2021). "Whatever influence VRK1 (or any other protein) might have on ER- tumor cells, no impact on relapse-free survival will be observed if the influence does not affect a rate-limiting step or push cells past a crucial barrier." (PMID 30180179, 2018). "Similarly, we observed higher levels of VRK1 in HCC tumor tissue and cell lines than in corresponding non-tumorous liver tissue and normal liver cells." (PMID 26375549, 2015).
tumor (continued). "Furthermore, inhibition of histone H4 acetylation impairs DDR, which by itself may not be enough, but can cooperate with VRK1 inhibition in the elimination of tumor cells." (PMID 37179361, 2023). "We evaluated the kinases VRK1 and VRK2, which are known to play multiple roles in cellular proliferation, cell cycle regulation, and carcinogenesis, and as such are potential predictors of tumor response and may aid in identifying patients who could benefit from NACRT." (PMID 27456229, 2016). "The data revealed that VRK1 showed a strong nuclear staining and demonstrated a significant increase in HCC tumor tissues compared with the adjacent non-tumor tissues." (PMID 40234378, 2025). "Given the lack of prior reports on VRK1's role in CRC, we examined VRK1 expression in both unpaired and paired CRC tumor and adjacent non-tumor tissues using data from the TCGA database." (PMID 40384864, 2025).